OR4F3 (olfactory receptor family 4 subfamily F member 3)
Description:
Odorant receptor.
Tractability: Antibody: UniProt places it where antibodies can reach, with medium confidence; UniProt predicts a signal peptide or a membrane-spanning region; its Gene Ontology location is reachable by antibodies, with medium confidence.
Gene: Protein-coding gene on chromosome 5 (181,367,268 to 181,368,262, forward strand). Ensembl gene ENSG00000230178.
Subcellular location: Cell membrane
Pathways (Reactome):
Sensory Perception: Expression and translocation of olfactory receptors
Gene Ontology:
Molecular function: protein binding; olfactory receptor activity; G protein-coupled receptor activity
Biological process: detection of chemical stimulus involved in sensory perception of smell; G protein-coupled receptor signaling pathway
Cellular component: plasma membrane; membrane
Homologues: Orthologues: rat Or4f7 (83% identical), rat Or4f7c (82% identical), mouse Or4f7 (82% identical). Paralogues in human: OR4F16 (100% identical), OR4F29 (100% identical), OR4F21 (99% identical), OR4F15 (71% identical), OR4F6 (67% identical), OR4F4 (57% identical), OR4F5 (57% identical), OR4F17 (56% identical), OR4K5 (53% identical), OR4K17 (53% identical), OR4K15 (51% identical), OR4K1 (51% identical), and 116 more.
Diseases named in the same sentence as OR4F3 in open-access papers:
OR4F3 is named in the same sentence as 2 diseases in open-access papers, as found by Europe PMC text mining. Sharing a sentence is not in itself a finding about the gene and the disease. The quoted sentences say what the papers report.
chronic hepatitis B (1 paper, 2016). "We assessed OR4F3 and OR4F17 copy number levels by absolute qPCR in healthy controls (Con, n = 5), chronic hepatitis B patients (CHB, n = 10), hepatitis B virus-liver cirrhosis patients (HBV-LC, n = 10), and hepatitis B virus- HCC patients (HBV-HCC, n = 10)." (PMID 26769853, 2016).
OR4F3 also shares sentences with these, for which no sentence is quoted: liver cirrhosis (1 paper).